CXCR1 (C-X-C motif chemokine receptor 1)
Diseases named in the same sentence as CXCR1 in open-access papers (continued):
Sharing a sentence is not in itself a finding about the gene and the disease.
breast carcinoma (continued). "In addition, CXCR1 was expressed in almost all breast cancer cells, mainly expressed in the cytoplasm of tumor cells, but rarely expressed in the nucleus." (PMID 28454081, 2017). "Meanwhile, almost all breast cancer cells expressed chemokine receptor CXCR1 with deep staining." (PMID 28454081, 2017). "Chemokine receptor CXCR1 is lowly expressed in normal breast tissue and breast fibroadenoma, but highly expressed in breast cancer, hinting that it might be used as an indicator to predict benign or malignant breast disease." (PMID 28454081, 2017). "After neo-adjuvant chemotherapy, CXCR1 expression in breast cancer tissues decreased." (PMID 28454081, 2017). "Though the fraction of CXCR1 expressing cells detected in MDA-MB231 was relatively high (> 10%) as compared to data reported in other breast cancer cell lines, in agreement with previous results, a significant enrichment of the CXCR1 positive cells was observed." (PMID 26517518, 2015). "CXCR1 blockade retards viability of breast cancer stem cells and reduces metastasis." (PMID 22936990, 2012). "Interestingly, other studies have demonstrated that the IL8/CXCR1 signaling is important for breast cancer cell invasion and predominantly active in cells with the cancer stem cell (CSC) phenotype when compared to non-CSCs." (PMID 23062209, 2012). "Agents targeting IL8 or its receptor CXCR1 may be useful for the treatment of HER2/HER3/IL8-positive breast cancers with invasive traits." (PMID 23062209, 2012). "A more-detailed study of the exact mechanism of the role of IL8 in invasion and intravasation in primary mammary tumors, and whether that uses the CXCR1 or CXCR2 receptors on the tumor cells or a paracrine interaction with the tumor stroma, is under way." (PMID 23113900, 2012). "Interestingly, these chemokine receptors, with the exception of CXCR1, have been shown to play a role in metastasis of mammary carcinoma." (PMID 20419088, 2010). "Inhibition of CXCR1 could compromise tamoxifen resistance in BQ overexpressing breast cancer." (PMID 35054486, 2022). "It has been reported that overexpression of CXCR1/2 could promote metastasis of breast carcinoma." (PMID 33324682, 2020). "CXCR1/2, members of the chemokine receptor family, have been studied in several types of cancer, showing a close correlation with drug resistance, survival, growth, angiogenesis, invasion and metastasis in breast cancer, melanoma, pancreatic cancer and colon cancer." (PMID 23420470, 2013). "Notably, a recent study characterized expression of the CXCL-8 receptor CXCR1 on breast cancer stem cells, which we believe to be the most aggressive tumor subpopulation, and described CXCR1 blockade decreases the docetaxel-amplified cancer stem cell population." (PMID 23342280, 2012). "Furthermore, the heterogeneous cell populations that comprise several cultured breast cancer cell lines have been shown to be inter-dependent, and survive via a paracrine CXCR1/IL8 pair, the receptor expressed on the ALDH+ tumor initiating cell compartment and the ligand by the tumor bulk cells." (PMID 21541292, 2011). "Neutralizing antibodies against GCP‐2, small molecule inhibitors for the CXCR1/CXCR2 receptors, and for CREB have already been shown to reduce tumor progression in breast cancer." (PMID 41258756, 2025). "For example, in breast cancer models, treatment with chemotherapy was found to induce TNF-α activation of NF-κB to increase CXCR1/2 expression, to reduce sensitivity to therapy." (PMID 40299479, 2025). "The conditioned medium from AGEs-exposed cancer-associated fibroblasts (CAFs) triggers paracrine activation of IL-8/CXCR1/2, leading to increased migratory and invasive characteristics in MDA-MB-231 breast cancer cells." (PMID 39830522, 2024). "By binding to its receptors, CXCR1 and CXCR2, IL-8 supports breast cancer progression by promoting tumor cell invasion and metastases." (PMID 37762330, 2023).
breast carcinoma (continued). "There is robust literature on breast cancer, specifically TNBC, on the ability to target CXCR1 and the CSC population that expresses it." (PMID 36831112, 2023). "This AGE-RAGE driven IL-8/CXCR1/2 instigation in CAFs incited the attainment of characteristics pertaining to migration and invasion in MDA-MB-231 breast cancer cells in vitro." (PMID 37970208, 2023). "Next, using a conditioned medium from AGEs-exposed CAFs, we determined that IL-8/CXCR1/2 paracrine activation induces the acquisition of migratory and invasive features in MDA-MB-231 breast cancer cells." (PMID 35954247, 2022). "Molecular subtype analysis revealed CXCR1 is significantly lower in triple negative than in luminal A, B and HER2 enriched breast cancers." (PMID 35754051, 2022). "Apart from CXCR1, CXCR2 has been shown to modulate the development, progression and drug response of breast cancer." (PMID 35054486, 2022). "Small-molecule antagonists of CXCR1/2, including SCH479833 and SCH527123, exerted anti-tumor activity in xenograft models of breast cancer, CRC, spontaneous colon cancer liver metastasis, and melanoma." (PMID 33603130, 2022). "Several previous studies have shown that CXCL8 which is a secreted protein functions with its receptors, CXCR1 and CXCR2, to promote the progression of some cancers, such as breast cancer, prostate cancer, lung cancer, and CRC." (PMID 35300114, 2022). "Activation of several Gi/o-coupled chemokine receptors, including CCR2, CXCR1, and CXCR2, by their cognate ligands was found to stimulate CSC activity in HER2+ breast cancer." (PMID 35406489, 2022). "CXCR1, one of the receptors for CXCL8, has been identified as a druggable target on breast cancer cancer stem cells (CSC)." (PMID 34476645, 2021). "Reparixin, an investigational allosteric inhibitor of CXCR1, reduced CSC in breast cancer (BC) xenografts both as single agent and in combination with taxane chemotherapy." (PMID 34476645, 2021). "Targeting CXCR1/2 receptors reduced BCSC activity in HER2 positive breast cancer ex vivo in metastatic and invasive human breast cancers." (PMID 33925129, 2021). "Blocking CXCR1 and CXCR2 in mice with breast cancer with reparixin, a specific small-molecule inhibitor of CXCR1 and CXCR2, results in decreased levels of NETs." (PMID 34758877, 2021). "Along with this, Reparixin, a CXCR1 inhibitor, was effective in treating several NOD/SCID mice breast cancer models." (PMID 34944943, 2021). "Examples of this include, the bioactive lipid, lysophosphatidic acid, and its receptor, LPAR-1 in breast cancer, chemokines, CXCL8/IL8 and CXCR1 and CXCR2 in melanoma, pancreatic cancer and gastric tumors and CXCL12 and CXCR4 in multiple cancers." (PMID 33329395, 2020). "ELR+ CXC chemokines such as CXCL1 and CXCL8, as well as their CXCR1/CXCR2 receptors, have been demonstrated to be significant factors in promoting CSC enrichment in breast cancer." (PMID 32582148, 2020). "CXCR1, one of the receptors for CXCL8 (IL-8), was identified on ALDH+ breast cancer CSC, and the addition of recombinant CXCL8 increased the CSC population and its propensity for invasion." (PMID 31924241, 2020). "In this regard, we do recognize that the main weakness of our study is the lack of experimental evidence supporting the antitumor activity of IL-8- or CXCR1/2-neutralizing antibodies in cultured and xenografted HRG-overexpressing/ER+ breast cancer cells." (PMID 33086721, 2020). "Chemokine receptor 1 (CXCR1), a receptor for CXC ligand 8 (CXCL8), which is a proinflammatory chemokine, is one of the actionable receptors expressed in breast cancer stem cells." (PMID 31013960, 2019). "Most of the reports in breast cancer bone metastasis evaluating chemokines CXCL6 and CXCL8 focus on CXCR1, expressed by osteoclasts." (PMID 30871004, 2019). "This mini review focuses on preclinical and clinical results obtained by interfering with chemokine receptors CXCR1 and CXCR2 in breast cancer." (PMID 30788286, 2019).
breast carcinoma (continued). "Considering a potential correlation between CXCR1/2 expression and ALDH activity reported in breast carcinoma, we tested how LDX treatment affects ALDH+ melanoma cells." (PMID 28129639, 2017). "Targeting IL-8 or its receptors CXCR1/CXCR2 has been shown to suppress tumor growth and induce cancer cell apoptosis in colon and breast cancer mouse models." (PMID 28881741, 2017). "We have previously shown that human epithelial breast cancer cells undergoing an EMT via overexpression of brachyury markedly upregulate the expression of IL-8 and its receptors, CXCR1 and CXCR2." (PMID 27248176, 2016). "In fact, CXCR1 was found, to be overexpressed in a highly tumorigenic subset of cells expressing the breast stem cell marker ALDH1 in a series of breast cancer cell lines as well as on mammospheres grown in vitro from patients' tumor samples." (PMID 26517518, 2015). "Also, small molecule inhibitors for the CXCR1/CXCR2 receptors are already in clinical trials for liver metastasis in colon cancer, breast cancer, and other indications." (PMID 41258756, 2025). "Taken together, our study implicates CXCL1 as a critical role in ERBC growth and metastasis via crosstalk with fibroblast and cotargeting CXCR1/2 and CDK4/6 could potentially overcome endocrine resistant breast cancer." (PMID 38393465, 2024). "CXCR1, one of the receptors for CXCL8 (IL‐8), is identified in ALDH1‐positive breast cancer CSCs." (PMID 36694633, 2023). "While not abundant in cancer cells, CXCR1 was identified on breast cancer stem-like cells (CSCs) where it plays a major role in regulating the breast CSCs and surrounding cancer cell survival via Fas-ligand mediated pathways." (PMID 35754051, 2022). "Thereafter, we assessed that IL-8, secreted in the conditioned medium collected from the AGEs-stimulated CAFs, acts in a paracrine manner through the cognate receptors CXCR1/2, empowering the acquisition of a spindle-like morphology and the actin polymerization in MDA-MB-231 breast cancer cells." (PMID 35954247, 2022). "Reparixin (R), an investigational oral inhibitor of CXCR1, was safely administered to metastatic breast cancer patients in combination with paclitaxel (P) and appeared to reduce CSC in a window-of-opportunity trial in operable breast cancer." (PMID 34476645, 2021). "CXCR1, one of the receptors for CXCL8, has been identified on breast cancer ALDH + CSC." (PMID 34476645, 2021). "Indeed, another study focused on blocking the IL-8 receptor CXCR1 using repertaxin, which selectively depleted CSC population in human breast cancer lines, confirming the role of this interleukin in maintaining the tumor stem population." (PMID 33059744, 2020). "CXCR1, one of the receptors for CXCL8, was identified on breast cancer (BC) CSCs." (PMID 31924241, 2020). "Overall, these findings suggest that IL-8 participates in the HRG-driven endocrine resistance program in ER+/HER2- breast cancer and might illuminate a potential clinical setting for IL8- or CXCR1/2-neutralizing antibodies." (PMID 33086721, 2020). "The expression of CXCR1 in breast cancer tissues was higher in patients with negative hormone receptors, positive Her2, worse cell differentiation, more lymph node metastasis and later pathology stage." (PMID 28454081, 2017). "The expression of chemokine receptor CXCR1 in biopsies of breast carcinoma was not correlated with the reaction to neo-adjuvant chemotherapy (P > 0.05), while the expression in surgical specimens was related to the reaction to chemotherapy (P < 0.05)." (PMID 28454081, 2017). "Breast cancer patients treated with chemotherapeutic drugs exhibited poor survival rate (66.7 vs 282.8 months, P=0.00071) and shorter disease-free survival time if their tumor samples expressed high level of IL8, CXCR1, CXCR2 genes and Wnt target genes." (PMID 28703802, 2017).
breast carcinoma (continued). "We demonstrate that the induced migration of a2Neuɸ is hampered significantly by anti-IL-8 neutralizing monoclonal antibody as well as by reparixin; a CXCR-1 and CXCR-2 inhibitor that is used in phase 2 clinical trial for Triple negative breast cancer treatment." (PMID 27845385, 2016). "Moreover, it has previously identified CXCR1, by gene expression profiling, as being overexpressed in cancer cells expressing the stem cell marker ALDH in a series of breast cancer cell lines." (PMID 26517518, 2015). "Breast cancer SK-BR-3, MDA-MB-231 and MCF10A cell lines were transfected by using Polyamidoamine (PAMAM) dendrimers and constructs encoding a luciferase/PE38 under the control either of the CMV or/CXCR1 promoter with or without the insertion of a bFGF 5′UTR." (PMID 36136517, 2022). "It is widely accepted that CXCR1 and CXCR2 are essential for the initiation and growth of human tumors, thus serve as the novel therapeutic targets for many solid tumors, including lung cancer, breast cancer, prostate cancer, ovarian cancer, liver cancer and melanoma." (PMID 35768814, 2022). "Interestingly, CXCR2 could be also a potential cancer stem-like cell marker, as a costaining of some breast cancer cells with NANOG and SOX2 has been reported and also that CXCR1/2 inhibition decreases mammosphere formation." (PMID 32727083, 2020). "In keeping with the critical role of IL-8 in cancer stemness, a function-blocking antibody against its receptor, CXCR-1, or a small-molecule inhibitor of CXCR-1 and CXCR-2, repertaxin, could deplete CSCs and inhibit tumor aggressiveness in human breast cancer xenografts." (PMID 31417869, 2019). "In keeping, breast cancer CSC were shown to proliferate in vitro in response to the addition of exogenous CXCL8 while a small molecular weight antagonist of CXCR1/2 (reparixin) or a blocking anti-CXCR1 (but not anti-CXCR2) monoclonal antibody were both able to deplete CSC in vitro." (PMID 30788286, 2019). "Importantly, pharmacological inhibitors of CXCR1/2 are already in clinical trials for several inflammatory diseases including COPD, asthma, and rheumatoid arthritis as well as for certain cancers including breast cancer and melanoma." (PMID 30185911, 2018). "Reparixin is an investigational, non-competitive allosteric inhibitor of the IL-8 receptors CXCR1 and CXCR2 and it has been investigated as a potential novel antineoplastic agent in synergy with standard chemotherapy targeting the CXCR1+ breast cancer stem population." (PMID 28423567, 2017). "Finally, various orally active small-molecule non-competitive antagonists of CXCR1 and CXCR2, such as SCH527123 (Merck), repertaxin (Dompé, Milan, Italy), and SCH479833 (Merck, Whitehouse Station, NJ, USA), have demonstrated anti-tumor effects in breast cancer xenograft models." (PMID 36835413, 2023).
melanoma (55 papers, 2004 to 2025). A malignant, usually aggressive tumor composed of atypical, neoplastic melanocytes. "In contrast, loss of CXCR2 or inhibition of CXCR1/CXCR2 in melanoma progenitor cells is associated with expression of genes associated with inflammation, T cell recruitment, pluripotency, and reduced tumorigenicity." (PMID 37270599, 2023). "Genetic loss of Cxcr2 or pharmacological inhibition of CXCR1/CXCR2 during melanoma tumor induction resulted in key changes in gene expression that reduced tumor incidence/growth and increased anti-tumor immunity." (PMID 37270599, 2023). "Several studies have indicated that the upregulated CXCR1 is associated with enhanced proliferation and invasiveness in melanoma cells; moreover, it is suggested that IL-8 and its receptor promote liver metastasis in colorectal cancer." (PMID 37240247, 2023). "Here, we initiate a preclinical study using murine BRAFWT murine B16-F10 melanoma and NRASmut 1014 melanoma cells to examine the effectiveness of combining the CXCR1/2 antagonist, SX-682, with the CDK4/6 inhibitor, palbociclib." (PMID 40904502, 2025). "MDSCs express the CXC chemokine receptor 1 and 2 (CXCR1/2), and their ligands are produced by melanoma cells." (PMID 40904502, 2025). "Currently, a phase I clinical trial has also been started in melanoma combining SX-682 (CXCR1/2 inhibitor) with ICI (NCT03161431)." (PMID 39630608, 2024). "The evidence in melanoma is slowly building for the CSC-like melanoma state expressing CXCR1, leaving a significant avenue for future evaluation." (PMID 36831112, 2023). "The overexpression of CXCL8 in melanoma is associated with disease progression, as an increased expression of CXCL8 and CXCR1 and CXCR2 has previously been associated with melanoma transition from a radial (early stage) to vertical (later stage) growth phase." (PMID 37170733, 2023). "Having established the importance of Cxcr2 in the development, growth, and TME of Braf/Pten melanoma tumors, we sought to evaluate the therapeutic potential of systemic CXCR1/CXCR2 inhibition." (PMID 37270599, 2023). "Pre‐clinical evidence suggests that tumour‐associated CXCR1 and CXCR2 overexpression correlates with increased proliferation and microvessel density and reduced apoptosis in melanoma." (PMID 37170733, 2023). "Remarkably, inhibition of FTO in melanoma has been found to suppress tumorigenicity and to increase the m6A levels in PD-1, CXCR1, and SOX10, hence enhancing the decay of these m6A-targeted mRNAs by YTHDF2." (PMID 35254013, 2022). "For example, the small-molecule antagonists, SCH-527123 and SCH-479833, that target CXCR2/CXCR1 were found to inhibit colon cancer and melanoma by decreasing neovascularization and increasing apoptosis of tumor cells." (PMID 36612163, 2022). "This has been demonstrated using small molecule inhibitors of CXCR1/2, which are able to abrogate melanoma cell motility and to induce apoptosis by inhibiting the Akt pathway." (PMID 34830780, 2021). "It is well-known that interleukin-8 (IL-8), which regulates proliferation and metastasis in melanoma, and its receptors, CXCR-1 and CXCR-2, are expressed more in A375SM than in A375P." (PMID 32859054, 2020). "Inhibition of CXCR1/2 appears to be very promising as it targets both melanoma and immune cells, reducing tumor burden alone or in combination with immune checkpoint blockers." (PMID 30420855, 2018). "In this study, we assessed therapeutic aspects of a novel, dual small molecule CXCR1/2 inhibitor, Ladarixin, to attenuate development and progression of human melanomas characterized by different molecular defects." (PMID 28129639, 2017). "These molecules render the tumor microenvironment and facilitate progression and metastatic dissemination of melanomas via autocrine and paracrine activation of CXCR1 and CXCR2 chemokine receptors." (PMID 28129639, 2017). "It has been reported that the use of CXCR1/CXCR2-specific antibodies in vitro can inhibit melanoma tumor growth." (PMID 28454081, 2017).